ABCA4 (ATP binding cassette subfamily A member 4)
Diseases named in the same sentence as ABCA4 in open-access papers (continued):
Sharing a sentence is not in itself a finding about the gene and the disease.
retinopathy (continued). "Our results seemingly conflict with these earlier studies, assuming that photoreceptor loss is the source of retinal sensitivity loss in ABCA4-associated retinopathy and that ONL thickness closely correlates with photoreceptor density in animal models." (PMID 35076026, 2022). "Currently, AON-based therapies are extensively studied for ABCA4-associated retinopathies due to the high proportion of splice-affecting variants, yet none have entered clinical trials." (PMID 33924840, 2021). "Since then thismouse, which has also been generated independently by other groups, has been the main and only animalmodel for studying ABCA4-associated retinopathy." (PMID 32278709, 2020). "The actualprevalence of ABCA4 -associated retinopathy is very difficult toestimate due to enormous clinical and genetic heterogeneity, variable age of onset,and (still) incomplete genetic data." (PMID 32278709, 2020). "Perhaps the most unusual feature amongst the triad is theobservation that the proximal tissue surrounding the optic nerve is sparedof disease changes in ABCA4-associated retinopathy." (PMID 32278709, 2020). "Ofadditional interest is the fact that differences between the two centers exist inboth the overall sex balance in ABCA4-associated retinopathy andseparately in the hypomorph subgroups." (PMID 32278709, 2020). "ABCA4-associated retinopathy shows abroad spectrum of clinical expression, with onset ranging from as early as 5 yearsof age to as late as 70 years." (PMID 32278709, 2020). "We cannot exclude that there are thus farmissed variants, especially in deep-intronic sequences, on the allele carrying thep.(Asn1868Ile) in ABCA4-associated retinopathy cases, which wouldrender these alleles fully penetrant." (PMID 32278709, 2020). "In this way, small regions ofthe ABCA4 locus were sequenced in genetically unsolvedABCA4-associated retinopathy cases." (PMID 32278709, 2020). "In this study, we assessed variants in intron 36 of ABCA4 and their potential involvement with ABCA4-associated retinopathy." (PMID 32653833, 2020). "ABCA4‐retinopathy was the most frequent cause accounting for 21% of cases, with the confirmed UAE founder mutation c.5882G>A p.(Gly1961Glu)/c.2570T>C p.(Leu857Pro) in 25%." (PMID 32783370, 2020). "Similar lesions of chorioretinal atrophy aretypically numerous (multifocal) and observed in the background of more advancedfleck stages with most other ABCA4-associated retinopathy cases." (PMID 32278709, 2020). "In ABCA4-associated retinopathy, lipofuscinaccumulation exerts a toxic effect causing cell death of neuroretinal and/orRPE cells, mainly in and around the macula." (PMID 32278709, 2020). "Monitoring the size of the atrophic lesion has been the primary outcomemeasure of most ABCA4-associated retinopathy clinical trials todate." (PMID 32278709, 2020). "The first animal model for ABCA4-associated retinopathy,the Abca4 knockout (KO) mouse(Abca4−/−), was introduced in 1999." (PMID 32278709, 2020). "Adetailed discussion of differential diagnoses is presented in section 3, Phenocopiesof ABCA4-associated retinopathy." (PMID 32278709, 2020). "As themajority of genotyped ABCA4-associated retinopathy cases hasnot yet been screened for the presence of SVs and DI variants, we estimate that~2% of all ABCA4 alleles are SVs and ~10% are DIvariants." (PMID 32278709, 2020). "As described in more detail below, different structural variants (SVs) (in ~1% of all alleles) and 35different causal deep-intronic (DI) variants (in 4% of all alleles), have beenidentified in ABCA4-associated retinopathy cases." (PMID 32278709, 2020). "Our results strongly argue for the use of hair follicles as a model for the molecular analysis of the pathogenicity of ABCA4 variants in patients with ABCA4 retinopathies." (PMID 32413971, 2020).
retinopathy (continued). "Patients carrying the c.5196+1137G>A allele in trans with known disease alleles had clinical presentations within the spectrum of ABCA4 retinopathy, supporting the pathogenicity of the allele." (PMID 32653833, 2020). "Consistent with this modelis the histopathological observation of lipofuscin-like autofluorescence in the coneinner segments of the retina of a patient with fundus flavimaculatus(ABCA4-associated retinopathy)." (PMID 32278709, 2020). "In a larger study of 125international ABCA4-associated retinopathy cases carryingp.(Asn1868Ile) in trans with a severe or deleterious allele andfully sequenced for variants in the ABCA4 locus, 79 (63%) werefemale and 46 (37%) were male." (PMID 32278709, 2020). "At the same time, new researchavenues have opened to unravel the unexplained differences in disease expressionbetween ABCA4-associated retinopathy cases, both within and betweenfamilies." (PMID 32278709, 2020). "ABCA4‐associated retinopathies often affect both photoreceptor and RPE in a manner that is not fully elucidated, but which originally involves a defective retinal clearance from the photoreceptor." (PMID 32212312, 2020). "Previously, a few variants in intron 36 potentially causing ABCA4-associated retinopathy have been described, including an in silico analysis of the splicing defects they exert." (PMID 32653833, 2020). "Another emerging important area is the concept of geneticmodifiers in the ABCA4 locus and in the genome; i.e., bothcis- and trans-modifiers forABCA4-associated retinopathy." (PMID 32278709, 2020). "The fraction ofphenocopies, i.e., cases with ABCA4-associated retinopathy-likephenotypes but with causal mutations in genes other than ABCA4,is still 10–15% of all cases, even in the most advanced centers, butthese are most often solved with WES." (PMID 32278709, 2020). "This review provides an in depthassessment of the cumulative knowledge of ABCA4-associated retinopathy –clinical manifestations, genetic complexity, pathophysiology as well as currentand proposed therapeutic approaches." (PMID 32278709, 2020). "Screening of large cohorts of familial casesof ABCA4-associated retinopathy will continue helping to decipherthe penetrance of selected ABCA4 alleles on a specific geneticbackground." (PMID 32278709, 2020). "As theABCA4 gene is expressed at a very low level in non-ocularhuman tissues, we also employed minigenes to analyze NCSS variants previouslyidentified in ABCA4-associated retinopathy cases." (PMID 32278709, 2020). "In childhood-onset ABCA4-associated retinopathy, the earliest stages of macular atrophy involve the parafovea and spare the foveola." (PMID 29310964, 2018). "This work represents the first detailed description of the earliest anatomic changes that occur in childhood-onset ABCA4-associated retinopathy." (PMID 29310964, 2018). "In our clinical report, the combination of ocular history, fundus imaging and electroretinography led to a diagnosis of a rapidly progressive retinopathy in a young patient with a severe ABCA4 homozygous variant." (PMID 24444108, 2014). "Several systems have been employed for the study of ABCA4-associated retinopathy." (PMID 40693713, 2025). "Because missense variants are associated with the majority of ABCA4-related retinopathy, their biochemical characterization using heterologous expression in cell culture has been of great interest, shedding light on their effect on folding, traffic, and/or function of the protein." (PMID 40693713, 2025). "This might explain why the majority of ABCA4-associated retinopathy is largely restricted to macular regions despite the uniform expression of ABCA4 across all photoreceptors, except in the context of two biallelic null alleles." (PMID 39971915, 2025). "PROM1 and PRPH2 variants have also been reported to act as modifiers of ABCA4-related retinopathy." (PMID 40960229, 2025). "ABCA4 retinopathy causes disease on a loss-of-function mechanism." (PMID 40960229, 2025).
retinopathy (continued). "Various mutation-specific treatments are being developed for ABCA4-associated retinopathy." (PMID 39201545, 2024). "The implementation of these novel approaches might lead to the identification of novel (likely rare) SVs, which have, to date, been missed in ABCA4-associated retinopathy cases." (PMID 38892127, 2024). "This ABCA4-associated retinopathy is highly heterogeneous both clinically and genetically." (PMID 37940365, 2024). "These are promising areas of research that could potentially lead to effective treatments for ABCA4-associated retinopathy, but more research is required to determine their safety and effectiveness in clinical trials." (PMID 37779911, 2023). "Of note, NIR-AF images are rarely recorded in clinical routine due to their lower contrast, but clinical information encoded in NIR-AF images of patients with ABCA4-related retinopathy may be functionally relevant and may uncover early pathology." (PMID 37336979, 2023). "Quantitative analysis of photoreceptor laminae thinning in ABCA4-related retinopathy may provide an opportunity to classify allele severity in an interval-scaled manner analogous to a previous perimetry-based study." (PMID 35076026, 2022). "Different compounds with a variety of actions have been tested for therapeutic intervention in ABCA4-associated retinopathy; some are related to antioxidant and anti-inflammatory actions, and others are based on the ability to halt/slow lipofuscin accumulation." (PMID 35739983, 2022). "However, it should be pointed out that patients with phenotypes within the spectrum of ABCA4-retinopathies and one variant in ABCA4 would first benefit from whole ABCA4 gene sequencing in search of known deep-intronic variants, before exome sequencing." (PMID 35260635, 2022). "Furthermore, 20 variants among 35 deep-intronic or near-exon variants were reported to have deleterious or severe effects in ABCA4-associated retinopathy, based on in vitro splice assays and analysis of photoreceptor progenitor cells." (PMID 36566289, 2022). "Furthermore, potentially pathogenic ABCA4 alleles have a population frequency of 1:20, underscoring the impact of ABCA4 in retinopathies." (PMID 35154257, 2021). "Theentire ABCA4-associated retinopathy continuum isbased on a loss-of-function mechanism, whether complete, or partial;i.e., haploinsufficiency, as in carriers of ABCA4variants." (PMID 32278709, 2020). "Given the association of distinct c.5196+1137G>A haplotypes with patients with ABCA4-associated retinopathy, we explored whether this was also true for this variant." (PMID 32653833, 2020). "The aim of the present study was to evaluate whether human hair follicles may be used for molecular analysis of the ABCA4 gene splice-site variants in patients with ABCA4 retinopathies." (PMID 32413971, 2020). "Finally, there are also several mutation-specific therapies underdevelopment for ABCA4-associated retinopathy." (PMID 32278709, 2020). "Sparing of this region oftenpersists in ABCA4-associated retinopathy, both structurallyand functionally but progressively lost at later disease stages; however,its etiological basis is unknown." (PMID 32278709, 2020). "In comparison with a perfect gender balance (50%/50%)observed in 284 bi-allelic ABCA4-associated retinopathy probandsnot carrying presumed hypomorphic alleles, this was statistically significant(p = 0.018) (E. Runhart, M. Khan, F.P.M. Cremers, C-M.Dhaenens, unpublished data)." (PMID 32278709, 2020). "Here, we report that full-length ABCA4 transcript is highly expressed in human eyebrow hair follicles and may be thus considered useful for the molecular analysis of splice-site ABCA4 mutation consequences in patients with ABCA4 retinopathies." (PMID 32413971, 2020).
retinopathy (continued). "Although referral patterns might have biased our cohort towards a slightly exaggerated frequency of ABCA4-associated retinopathy, previous studies have likewise indicated that mutations in ABCA4 are the most common cause of central retinal dystrophies." (PMID 29555955, 2018). "Out of the remaining 60 patients, 7 patients (12%) revealed one potentially disease-causing variant in a gene causing recessive retinopathy in combination with a phenotype usually associated with mutations in the respective gene (ABCA4, n = 5; CDH3, n = 1; CERKL, n = 1)." (PMID 29555955, 2018). "As with any other category of IRD, the selected treatment method for ABCA4-associated retinopathy may vary from mutation-specific techniques to more commonly used cell replacement, primarily dependent on the initial genetic abnormality and the stage of the disease at the beginning of therapy." (PMID 39201545, 2024). "However, ABCA4-associated retinopathies are clinically variable and genetically heterogeneous." (PMID 33841504, 2021). "Furthermore, the female-to-maleratio among all 1060 ABCA4-associated retinopathy cases at theColumbia center is 54:46 in the entire disease cohort and 57:43 in the sub-cohortwith the p.(Asn1868Ile) allele (100 cases) (J. Zernant, W. Lee, R. Allikmets,unpublished data)." (PMID 32278709, 2020). "In addition, we report the identification of six novel potentially pathogenic mutations thus extending the spectrum of the ABCA4 gene mutations and of three prevalent alleles which may facilitate the screening of Greek patients with ABCA4-related retinopathy." (PMID 29854428, 2018). "Our findings therefore suggest that therapeutic interventions are likely to work best in childhood-onset ABCA4-associated retinopathy if given very early, although it may be challenging to recruit such patients for clinical trials until convincing safety and efficacy data are available in adults." (PMID 29310964, 2018). "This case challenges conventional genotype–phenotype correlations for ABCA4 retinopathy and highlights the importance of comprehensive genetic analysis in patients with atypical IRD presentations." (PMID 41458191, 2026). "This case expands the recognized phenotypic variability of ABCA4‐retinopathy and highlights the critical importance of comprehensive genetic testing for reaching an accurate diagnosis in patients with IRDs, even when the clinical presentation is atypical." (PMID 41458191, 2026). "Future therapeutic strategies for ABCA4‐retinopathies, such as gene replacement therapy or CRISPR‐based gene editing, are under active investigation." (PMID 41458191, 2026). "ABCA4-related retinopathies also include a broader range of phenotypes, including fundus flavimaculatus, pattern dystrophy, and cone-rod dystrophy." (PMID 40960229, 2025). "They thus demonstrate the potential extremes in severity in ABCA4-retinopathy, likely influenced by disease modifiers, and reports such as these highlight the importance of efforts to identify potential modifiers in inherited retinal disease." (PMID 40824243, 2025). "This variability is indicative of a spectrum of a unified disease process known as ABCA4-related retinopathy." (PMID 41465088, 2025). "Further work is needed to investigate unidentified modifying factors influencing phenotypic variability in ABCA4-related retinopathies, to improve our understanding of the disease and prognostic accuracy." (PMID 40960229, 2025). "While the SMaRT-based therapy for ABCA4-related retinopathy is currently being evaluated in a clinical trial, the implementation of this strategy for other targets and improvement of the efficiency of SMaRT are very much needed." (PMID 40896583, 2025). "Several candidate genes associated with CQ/HCQ retinopathy were found with exome sequencing, including RP1L1, RPGR, RPE65, CACNA2D4, EYS, RP1, IMPG1 and ABCA4." (PMID 38548946, 2024).
retinopathy (continued). "ABCA4-related retinopathy is the most common inherited Mendelian eye disease in the world, with an estimated prevalence of 1:6578." (PMID 38674104, 2024). "There have been several studies demonstrating the identification of such RNA defects using augmented screening approaches in previously unsolved ABCA4‐mediated retinopathies and in some cases, their validation with functional midigene splicing assays." (PMID 36177499, 2023). "The company is planning future clinical development for patients afflicted with ABCA4-related retinopathies." (PMID 37834872, 2023). "ABCA4 retinopathy is a rare disease; given the size of our cohort, we would expect a small number of cases to be present in our sample." (PMID 37342033, 2023). "ABCA4 retinopathy typically has an age of onset <20 years, much younger than the age of participants in our cohort." (PMID 37342033, 2023). "An ongoing open-label phase 1/2 trial (NCT04545736) was initiated in 2020 through the National Eye Institute with an estimated enrollment of 45 patients with ABCA4 retinopathies including STGD1." (PMID 37834872, 2023). "For instance, R-AF in ABCA4-related retinopathy showed the combined information of SW-AF and NIR-AF alterations, hence allowing a more comprehensive analysis by means of only one image." (PMID 37336979, 2023). "This study quantifies prevalence of phenotypic groups based on retinal function in a uniquely large single-center cohort of patients with electrophysiologically characterized ABCA4 retinopathy and shows applicability of machine learning." (PMID 36178783, 2022). "A phenotypic feature of RDH12 retinopathy is sparing of the peripapillary region, pathognomonic of ABCA4-retinopathy." (PMID 35162940, 2022). "ERGs were available from 597 individuals with ABCA4 retinopathy (1189 eyes), including 497 with at least two recognized pathogenic variants." (PMID 36178783, 2022). "To date, about 1700 different pathogenic variants in ABCA4 have been identified in STGD and other related retinal phenotypes collectively known as ABCA4-associated retinopathies." (PMID 36051698, 2022). "A good example of this toxicity is ABCA4-retinopathy where toxic products of vitamin A accumulate excessively in the retina." (PMID 35162940, 2022). "For example, in ABCA4 retinopathy, the BCVA and lesion area involvement were significantly more severe in the patients with two null variants than in patients harboring null and missense variant or two missense variants." (PMID 35806404, 2022). "Our current study supports the potential of the use of RPE cells as “disease-in-a-dish” biological system to test emerging therapies for ABCA4-mediated retinopathies." (PMID 36359858, 2022). "Although abundant lipofuscin accumulation is involved in the aetiology of certain retinal diseases (e.g., AMD, Best disease and ABCA4-retinopathy), it accumulates at a lower level also with age in the RPE of healthy eyes." (PMID 35162940, 2022). "We expected to observe ONL thinning distant to the boundary of EZ-loss in a subset of patients given retinal sensitivity and electroretinogram (ERG) findings from previous studies of ABCA4-related retinopathy." (PMID 35076026, 2022). "Several studies have established the prognostic value of this classification in ABCA4 retinopathy, informing patient counseling and management and potentially influencing the selection of candidates for future interventions." (PMID 36178783, 2022). "In ABCA4-related retinopathy, a recent study predicted ERG Results through OCT layer thickness with an accuracy of 97.47 ± 2.03%." (PMID 33767409, 2021). "Information regarding the imaging and characterisation of the different ABCA4 retinopathies (ABCA4R) is described in a review." (PMID 34440414, 2021). "Danish cohort data were taken from a published cohort that included 31 ABCA4-related retinopathy patients, of which three had complex alleles and none were homozygous." (PMID 35154257, 2021).